UCP2 (uncoupling protein 2)
Diseases named in the same sentence as UCP2 in open-access papers (continued):
Sharing a sentence is not in itself a finding about the gene and the disease.
Hyperglycemia (continued). "The present study was undertaken to test the hypothesis that TRPV1 activation by capsaicin attenuates hyperglycemia-induced endothelial dysfunction through a UCP2-mediated antioxidant effect." (PMID 23607427, 2013). "TRPV1 activation by capsaicin might protect against hyperglycemia-induced endothelial dysfunction through a mechanism involving the PKA/UCP2 pathway." (PMID 23607427, 2013). "We hypothesised that TRPV1 activation by capsaicin attenuates hyperglycemia-induced endothelial dysfunction through a UCP2-mediated antioxidant effect." (PMID 23607427, 2013). "Finally, hyperglycemia-induced mitochondrial superoxide activates UCP-2, which subsequently impairs GSIS." (PMID 18167556, 2008). "Therefore, the high expression of UCP2 caused by UCP2-866G/A polymorphism is a high-risk factor not only for hyperglycemia but also for ARHL." (PMID 35966796, 2022). "A recent study showed that capsaicin can increase the level of UCP2, both in porcine iliac artery endothelial cells (PIECs) cultured in a high glucose medium and in db/db mice, and alleviate ROS production and endothelial dysfunction induced by high glucose or hyperglycemia." (PMID 36088760, 2022). "In addition, upregulation of UCP2 expression plays an important role in the restoration of hyperglycemia-induced endothelial dysfunction, which is due to the suppression of superoxide production and the elevation of NO production in the blood vessels and endothelial cells." (PMID 29490624, 2018). "Interestingly, increased UCP-2 activity results in defective glucose-induced insulin release from pancreatic beta-cells, which could explain the apparent hyperglycemia during hibernation." (PMID 24039826, 2013). "In addition, our results suggest that genipin might protect hyperglycemia-induced podocytes injury by inhibition of mitochondrial uncoupling protein 2 (UCP2)." (PMID 22848482, 2012). "In isolated mitochondria, hyperglycaemia induced an increase in the oxidation of palmitoylcarnitine and glycerol-3-phosphate (lipid-derived fuels) and a decrease in the oxidation of pyruvate (a mitochondrial fuel); in addition, increased UCP2 activity was observed." (PMID 23053476, 2012). "UCP2 is likely an upstream mediator of ROS generation and NLRP3 inflammasome activation in hyperglycemia-exacerbated I/R damage." (PMID 33735403, 2021). "Our results demonstrated that downregulation of renal mitochondria PRR via PRR shRNA delivery efficiently blocked hyperglycemia-induced dysfunction of mitochondria by reversing SOD2 levels, inhibiting UCP2 protein levels, and increasing ATP synthesis." (PMID 31406124, 2019). "Moreover, UCP-2 might function as an adaptive antioxidant defense to protect against the development of atherosclerosis in response to high fat and cholesterol diet and improve hyperglycemia-induced endothelial dysfunction." (PMID 25077985, 2014). "Additionally, increased expression of UCP2 induced by TRPV1 exerted a protective antioxidant effect on the liver in non-alcoholic fatty liver disease and on vascular endothelium during hyperglycemia." (PMID 41226458, 2025). "Hence, UCP2 is likely an upstream mediator of ROS generation and NLRP3 inflammasome activation after hyperglycemia-exacerbated I/R damage." (PMID 33735403, 2021). "In addition, another antiapoptotic substance, uncoupling protein 2 (UCP2), a proton transporter in the mitochondrial inner membrane, was also reported to be involved in RSV-induced cardioprotection during hyperglycemia." (PMID 32256959, 2020). "Consistently, we found that the glucose-induced mitochondrial ROS production is modest in the EA.hy926 venous endothelial cells compared to the microvascular endothelial cells, in which hyperglycemia does not alter the expression of UCP2." (PMID 27128320, 2016). "Increased expression of UCP-2 and decreased expression of UCP-3 in humans with chronic hyperglycemia may contribute to impaired glucose-stimulated insulin secretion." (PMID 18167556, 2008).
Hyperglycemia (continued). "However, the effect of UCP2 on NLRP3 inflammasome-mediated hyperglycemia and I/R damage is not clear." (PMID 33735403, 2021). "Hyperglycemia resulted in a more pronounced decline of Opa1in WT than in normoglycemic group in all endpoints including non-ischemic control; however, it did not further decrease Opa1 in UCP2-/- mice." (PMID 33061796, 2020).
atherosclerosis (35 papers, 2006 to 2025). A disease characterized by the build-up of fatty material and calcium deposition in the arterial wall resulting in partial or complete occlusion of the arterial lumen. "In the same vein, deficiency of Ucp2 resulted in defective apoptotic cell removal and was associated with development of atherosclerosis, whereas overexpression of Ucp2 enhanced efferocytosis." (PMID 32296442, 2020). "Several studies have shown that UCP2 deficiency causes vascular dysfunction and target organ damage in stroke, atherosclerosis and hypertension." (PMID 23607427, 2013). "Human genetic studies have confirmed these findings since the common G/A polymorphism at −866 upstream from Ucp2 promoter is linked to atherosclerosis, diabetes and multiple sclerosis." (PMID 21857957, 2011). "We wished to evaluate contributions of known UCP1 and UCP2 variants to metabolic traits in the Insulin Resistance and Atherosclerosis (IRAS) Family Study." (PMID 17397545, 2007). "Therefore, the main purpose of this study was to determine the possible underlying mechanisms responsible for the effect of exercise on ER stress and UCP2 deficiency-associated coronary vascular dysfunction in atherosclerosis." (PMID 34326395, 2021). "We further hypothesized that exercise training would mitigate UCP2 deficiency-associated vascular dysfunction through the restoration of UCP2 expression and reduction of oxidative stress in coronary arterioles of atherosclerosis." (PMID 34326395, 2021). "However, the direct effects of exercise on ER stress-mediated endothelial dysfunction and on ER stress-associated caspase-1 and UCP-2 signaling in atherosclerosis merit further examination." (PMID 29784903, 2018). "On the other hand, both obese and diabetic patients have associated vascular complications such as atherosclerosis and retinopathy where UCP2 may play a direct contributory pathogenetic role." (PMID 29163755, 2017). "Similarly, UCP2-deficient mice display elevated atherosclerosis, decreased endothelial nitric oxide levels and increased vascular adhesion molecule expression as well as increased salt-induced hypertensive changes." (PMID 24642125, 2014). "Among the study limitations we must acknowledge that, due to the cross-sectional design, we cannot determine whether the UCP2 polymorphism is causally associated with hs-CPR or the association is mediated through other atherosclerosis-associated conditions." (PMID 21029457, 2010). "Accordingly, our findings suggest that the upregulation of UCP2 expression by exercise training ameliorates vascular dysfunction through the reduction of UCP2 deficiency-derived ROS production in atherosclerosis and it might be regulated by PGC1α/PPAR-δ signaling." (PMID 34326395, 2021). "In addition, here we report that exercise training ameliorates ER stress and UCP2 deficiency-associated endothelial dysfunction in different vascular beds, coronary arterioles where mainly regulate blood flow to the cardiac muscle, in atherosclerosis." (PMID 34326395, 2021). "Given the importance of UCP1 and UCP2 genes in metabolism, we chose to evaluate the five promoter or coding variants in these two genes previously associated with metabolic phenotypes (above) for associations in families from the Insulin Resistance and Atherosclerosis (IRAS) Family Study." (PMID 17397545, 2007). "Taken together, these results suggest that vulnerable psEVs promote endothelial inflammation and atherosclerosis partially through miR‐497‐5p delivery and UCP2 suppression to modulate the ROS/TXNIP/NLRP3 pathway." (PMID 40391195, 2025). "Amongst, we focused on UCP2, a key mitochondrial antioxidant protein that has been reported to be protective against endothelial oxidative stress, inflammation, and atherosclerosis." (PMID 40391195, 2025). "UCP2 emerges as a promising therapeutic target for various vascular diseases, including atherosclerosis, diabetic vascular disease, hypertension, stroke, and peripheral vascular disease." (PMID 39920720, 2025).
atherosclerosis (continued). "Further mechanistic studies have revealed that TRPV6 regulates the PKA/UCP2 signaling pathway, thus modulating inflammatory response and cell apoptosis in atherosclerosis." (PMID 39742020, 2024). "UCP2 has demonstrated anti-inflammatory and antiapoptotic effects in various diseases, possibly involved in the development of atherosclerosis." (PMID 39742020, 2024). "Our study highlights the pivotal role of TRPV6 in mitigating apoptosis and inflammatory responses in atherosclerosis cell models via modulation of the PKA/UCP2 signaling pathway." (PMID 39742020, 2024). "This research is aimed at unravelling the intricate relationship between TRPV6, PKA, UCP2, and atherosclerosis." (PMID 39742020, 2024). "Our findings suggest that TRPV6, through the regulation of the same downstream signaling pathway, PKA/UCP2, inhibited apoptosis and inflammatory response in the atherosclerosis cell model." (PMID 39742020, 2024). "We further demonstrated that TRPV6 inhibited inflammatory response and apoptosis in atherosclerosis through the regulation of PKA/UCP2." (PMID 39742020, 2024). "Some of the first evidence for a role for UCP2 came in studies of atherosclerosis where UCP2 knockout mice showed much higher oxidative stress and larger atherosclerotic plaques than wild-type mice." (PMID 35628482, 2022). "High UCP2 levels exert a protective effect in heart diseases, atherosclerosis, and IS, whereas low UCP2 levels exert a detrimental effect." (PMID 35629388, 2022). "A protective role of UCP2 in atherosclerosis has also been suggested as mice transplanted with bone marrow from UCP2-/- mice demonstrated elevated oxidative stress and increased lesion size." (PMID 36497101, 2022). "Endoplasmic reticulum (ER) stress and uncoupling protein-2 (UCP2) activation are opposing modulators of endothelial dysfunction in atherosclerosis." (PMID 34326395, 2021). "The deficiency of UCP2 led to an accumulation of ACs in atherosclerotic plaques, to an enhancement of necrotic cores in the plaques and accelerated atherosclerosis in Ucp2−/− mice." (PMID 31766552, 2019). "A limitation of the current study is the absence of cellular and molecular expressions data of ER stress markers and key factors such as caspase-1, UCP-2, and eNOS affected by atherosclerosis and exercise training." (PMID 29784903, 2018). "We conclude that ER stress plays a significant role in endothelial dysfunction of resistance arteries in atherosclerosis and that exercise attenuates ER stress and regulates its critical downstream signaling pathways including eNOS, UCP-2 and caspase-1." (PMID 29784903, 2018). "Evidence of a direct role of UCP2 in the promotion of atherosclerosis in vivo was first obtained in the UCP2 gene-knockout mice that developed multiple atherosclerotic lesions in several districts, with a significantly shorter lifespan." (PMID 29163755, 2017). "The deletion of the UCP2 gene contributes to atherosclerosis lesion development in the knockout mice, also showing significantly shorter lifespan." (PMID 29163755, 2017). "Previous results have also suggested a protective role of UCP-2 against atherosclerosis showing an antiatherogenic effect in macrophages, ECs and VSMCs." (PMID 25077985, 2014). "Proposed functions of UCP2 include preventing the formation of ROS and atherosclerosis, participation in inflammation, body weight regulation, adaptive thermogenesis and aging." (PMID 24013271, 2013). "Therefore, it is plausible to hypothesize that functional UCP2 gene polymorphisms leading to reduced expression of UCP2 may be related to a proinflammatory status and possibly to the development and progression of atherosclerosis." (PMID 21029457, 2010).
atherosclerosis (continued). "UCP2 protects against atherosclerosis in animal models potentially through inhibition of ROS production in endothelial cells and inhibition of monocyte accumulation in the artery wall." (PMID 16968550, 2006). "Pharmacological targeting of miR‐497‐5p and UCP2 may represent novel therapeutic approaches to attenuate atherosclerosis development and progression." (PMID 40391195, 2025). "Finally, mechanistic investigations revealed that vulnerable psEVs promoted endothelial inflammation and atherosclerosis partially through miR‐497‐5p delivery and UCP2 suppression to activate the ROS/TXNIP/NLRP3 pathway." (PMID 40391195, 2025). "Also, we determine more in-depth underlying molecular mechanisms by which exercise training improves coronary endothelial function by regulating ER stress, TXNIP/NLRP3 inflammasome signaling cascades, and UCP2-regulated ROS generation in atherosclerosis." (PMID 34326395, 2021). "The protective effect of UCP2 on atherosclerosis has been studied, and its mechanism may be related to macrophage metabolism and thermogenesis." (PMID 35284500, 2021). "Uncoupling protein 2 (UCP2) is a mitochondrial transport protein, which is increasingly recognized as an important molecule in the defense of various cardiovascular diseases such as atherosclerosis, coronary heart disease, heart failure and hypertension." (PMID 35284500, 2021). "However, there is very little data regarding how exercise influences UCP2 signaling in atherosclerosis." (PMID 34326395, 2021). "However, little is known about the mechanistic link between ER stress, TXNIP/NLRP3 inflammasome activation, and UCP2 activity on coronary vascular dysfunction in atherosclerosis." (PMID 34326395, 2021). "The protective effect of UCP2 has also been studied in atherosclerosis." (PMID 30116205, 2018). "UCP2 in the cardiovascular system is being increasingly recognized as an important molecule to defend against various stress signals such as oxidative stress in the pathology of vascular dysfunction, atherosclerosis, hypertension, and cardiac injuries." (PMID 30116205, 2018). "However, further study is required to define the protective role of exercise in UCP-2-mediated vascular dysfunction in atherosclerosis." (PMID 29784903, 2018). "And previous study indicated that increasing expression of UCP-2 in vascular cells may prevent the development and progression of atherosclerosis in patients with increased ROS." (PMID 28683125, 2017). "Consistent with a protective role of UCP2 in the vasculature, transgenic low density lipoprotein receptor deficient mice lacking UCP2 in circulating cells exhibit increased atherosclerosis." (PMID 24642125, 2014). "Furthermore, we demonstrated that vulnerable psEVs promoted endothelial inflammation and atherosclerosis, partially through the delivery of miR‐497‐5p and subsequent suppression of UCP2, thereby activating the ROS/TXNIP/NLRP3 pathway, a well‐established mechanism of NLRP3 activation." (PMID 40391195, 2025). "However, during low-grade chronic inflammation, in conditions such as atherosclerosis, ROS produced by vascular macrophages can exert deleterious effects on the arterial wall including cell adhesion and migration, which can be reversed by UCP2 overexpression." (PMID 30116205, 2018). "Uncoupling protein-2 (UCP-2), which regulates mitochondrial ROS generation, may prevent a process of atherosclerosis and mitigate endothelial dysfunction with an increase in NO production in atherosclerosis and metabolic disorder." (PMID 29784903, 2018). "In atherosclerosis, berberine treatment inhibits inflammation in mouse macrophages (J774A.1) by inducing autophagy through AMPK/mTOR pathway and uncoupling protein 2 in mice." (PMID 34745081, 2021). "AMPK activation improves the function of endothelium by defending oxidative stress in atherosclerosis, as supported by AMPK-regulated UCP2 expression in ECs." (PMID 32679729, 2020).
atherosclerosis (continued). "It appears that UCP2 has a main function of controlling ROS generation in diabetes, obesity, and atherosclerosis, although it was originally considered as a modulator of nonshivering thermogenesis." (PMID 32679729, 2020). "UCP2 has been shown to regulate ROS production in immune and in non-immune cells during pathological conditions such as atherosclerosis, type I diabetes, infections, cerebral ischemia and EAE, thus protecting the organism from oxidative stress." (PMID 21857957, 2011). "However, no study has evaluated the exercise effects on UCP-2 in vascular dysfunction in any pathology including atherosclerosis." (PMID 29784903, 2018). "The suggestive experiments with cultured cells described here do not address directly whether berberine-enhanced UCP2 expression can reduce oxidative stress and atherosclerosis in vivo." (PMID 21980456, 2011).